ADAM8 (ADAM metallopeptidase domain 8)
Diseases named in the same sentence as ADAM8 in open-access papers (continued):
Sharing a sentence is not in itself a finding about the gene and the disease.
breast carcinoma (continued). "Therefore, human MDA-MB-231 breast carcinoma cells with ADAM8 knocked down, referred to as ADAM8-KD cells, as well as MDA-MB-231 scrambled control cells, referred to as ADAM8-Ctrl cells, have been used to examine their ability to interact with and migrate in dense extracellular 3D matrices." (PMID 37287457, 2023). "To dissect the effects of ADAM8 on oncoproteins mechanistically, we hypothesized that ADAM8 could alter the expression levels of distinct miRNAs such as miR-720, as previously shown for breast cancer cells." (PMID 35371977, 2022). "Also breast cancer cells require ADAM8 for efficient cell migration." (PMID 33314720, 2021). "Since ADAM8 expression was reported to elevate the expression and/or activity of matrix-metalloproteinase 9 (MMP9) in breast cancer cells, it seems to be likely that MMP9 hampered the fiber displacement generation of ADAM8-Ctrl cells." (PMID 37287457, 2023). "Based on these datasets, it can be deduced that ADAM8 enhances precocious metastatic events like transendothelial migration through upregulation of MMP-9 and liberation of PSGL-1 by breast cancer cells." (PMID 36910158, 2023). "ADAM8 enhances early metastatic events including transendothelial migration through upregulation of MMP-9 and liberation of PSGL-1 from breast cancer cells." (PMID 36910158, 2023). "The use of ADAM8 and MMP-9 antibodies diminished the transmigration of MDA-MB-231 cells, indicating that ADAM8 impacts the levels of transmigration of breast cancer cells by regulating MMP-9." (PMID 36910158, 2023). "Previously, we demonstrated that ADAM8-dependent MMP9 expression is mediated via the MAPK pathway and resulted in a strong correlation of ADAM8 and MMP9 in breast cancer-derived brain metastasis." (PMID 35371977, 2022). "In accordance, MDA-MB-231 were among those cell lines that showed a strong correlation between ADAM8 and MMP9 expression in our previous study on breast cancer-derived brain metastases." (PMID 35371977, 2022). "ADAM8 and MMP9 levels are correlated in GBM tissue samples as well breast cancer-derived brain metastasis." (PMID 35371977, 2022). "Several reports have shown that members of the ADAM family are overexpressed in human cancers such as ADAM8 in human renal cell carcinomas, ADAM15 in lung carcinoma, and ADAM17 in breast cancers." (PMID 34249950, 2021). "Leading-edge analysis (for genes that contributed most to enrichment in pathways) showed genes that are upregulated downstream of KRAS in lung or breast cancer (e.g., CXCL3, ADAM8, and L.I.F.)." (PMID 32455851, 2020). "Our results agree with and extend these findings, showing for the first time that ADAM8 initiates the induction of miR-720 via activation of the β1-integrin/ERK signaling cascade to promote migration and invasion in breast cancer cells." (PMID 27039296, 2016). "The expression of respective proteins (Trop2, CD49f, c-Met, CK8, CD44, ADAM8, CD146, TEM8, CD47) was verified by immunofluorescence on EpCAMpos (e.g. MCF7, SKBR3) and EpCAMlow/neg (MDA-MB-231) breast cancer cell lines." (PMID 26695635, 2015). "Of interest, basal-like breast carcinomas, which are typically highly aggressive and mostly TNBC, expressed the highest levels of ADAM8 mRNA compared to normal-like, luminal A and B, or HER2-overexpressing breast cancers." (PMID 24375628, 2014). "The combination of ADAM8 and ADAM12 activities measured in urine samples was shown to identify with 90% confidence breast cancer patients with invasive and metastatic disease." (PMID 24375628, 2014). "As ADAM8 was required to maintain the aggressive phenotype of TNBC cells in 3D-culture, we further investigated its role in breast cancer pathology." (PMID 24375628, 2014). "More recently, we have developed an ADP2-based ADAM8 IHC assay, which confirmed the ADAM8 expression rate in TNBC (36.11% = 22/61 samples) and expanded ADAM8 positivity to all breast cancers, i.e., 33.9% (166 of 490 samples) of breast tumors of any subtype were ADAM8+." (PMID 38675197, 2024).
breast carcinoma (continued). "Our mechanistic studies in breast cancer cells demonstrate that ADAM8 has no direct effect on cell proliferation or survival, but rather on the tumor cell surface and microenvironment." (PMID 38675197, 2024). "For the first time, these non-TNBC breast cancer samples were similarly found positive for ADAM8: 27.3%, 33.2% and 32.1% for HR−/HER2+, HR+/HER2− and HR+/HER2+ patient samples, respectively." (PMID 37568162, 2023). "Here, we demonstrate for the first time that ADAM8, a critical driver of tumor growth and spread, is expressed in about one third of all breast tumors, extending our published findings on TNBC to HR+ and HER2+ breast cancer." (PMID 37568162, 2023). "Another characteristic feature of ADAM8 is that ADAM8 dimers can be consistently identified on the surface of ERα-negative breast cancer cells, whereas they are absent on ERα-positive breast cancer cells." (PMID 36910158, 2023). "The analysis also revealed a similar ADAM8 positivity rate (~ 30%) in all other non-TNBC breast cancer subtypes, including HR−/HER2+ (6/22 = 27.3%), HR+/HER2− (100/301 = 33.2%) and HR+/HER2+ (9/28 = 32.1%), that had not been examined previously." (PMID 37568162, 2023). "This led to the identification of 490 primary breast cancer samples in good condition, including 412 with data on the expression of all 3 standard molecular markers for breast cancer (ER, PR and HER2), for evaluation of ADAM8 expression." (PMID 37568162, 2023). "Consistent with the notion that tumors with higher ADAM8 levels are characterized by increased angiogenesis, a positive correlation was found between ADAM8 and CD31 (PECAM1) mRNA expression in tumor samples from patients with basal-like breast cancer." (PMID 24375628, 2014). "In vivo, mammary tumors of shCtrl, but not shA8 animals, displayed a substantial increase in ADAM8 protein around necrotic areas." (PMID 24375628, 2014). "Moreover, using transwell membrane cultures, it has been shown that ADAM8 promotes the transendothelial migration in the initial steps of the metastastatic cascade through elevation of MMP9 and shedding of PSCL-1 of the cell surface of breast cancer cells." (PMID 37287457, 2023). "Moreover, itwas more effective than the parent monomeric compound in blockinginvasiveness in the breast cancer MDA-MB-231 cell line, thus supportingour hypothesis about the importance of inhibiting the active homodimerof ADAM8." (PMID 35111280, 2021). "Thus, the interaction of ADAM8 with TOCA1, and/or CIP4 could be worth a closer look as a potential mechanism driving breast cancer progression." (PMID 25825872, 2015). "While MMPs are connected to the malignant progression of several cancer types, including breast cancer, and MMPs-based cell migration has been demonstrated for 3D collagen fiber matrix assays, the role of ADAM8 has not yet been explored in these 3D collagen fiber matrices." (PMID 37287457, 2023).
pancreatic cancer (23 papers, 2014 to 2025). "For example, there is one particularly interesting member, ADAM8, whose expression level has been associated with poor clinical prognosis in several cancers, including breast and pancreatic cancer." (PMID 37287457, 2023). "In pancreatic cancer cells, knockdown of ADAM8 causes decrease in phosphorylated ERK1/2, MEK1/2 and Akt." (PMID 33314720, 2021). "Pancreatic ductal adenocarcinoma cell migration is associated with high ADAM8 expression and a peptidomimetic inhibitor of ADAM8 can suppress metastasis of implanted pancreatic tumour cells in vivo." (PMID 33314720, 2021). "According to the GEPIA2 and TCGA databases, NEAT1 is highly expressed in pancreatic cancer and is positively correlated with ADAM8." (PMID 39412616, 2025). "Low doses of propofol have been shown to inhibit pancreatic cancer cell proliferation, migration, and invasion by downregulating ADAM8 expression, an effect mediated by the suppression of specificity protein 1 (SP1), which regulates ADAM8 transcription." (PMID 40427200, 2025). "Targeting ADAM8 with the peptide mimetic has been shown to enhance survival in pancreatic cancer (KPC) mouse models by reducing tumour volume, limiting metastasis, and decreasing tumour cell invasion while preserving acinar structures." (PMID 40427200, 2025). "ADAM8 facilitated extracellular signal transmission in the local tumor environment of pancreatic cancer via the governed release of Lipocalin 2 and MMP-9." (PMID 36910158, 2023). "ADAM8 has been reported to be highly expressed in pancreas cancer or ductal adenocarcinoma, is coupled to poor clinical prognosis of cancer and seems to be linked to the effect of chemoresistance to medical treatment of cancers." (PMID 37287457, 2023). "In pancreatic cancer, propofol was found to downregulate the expression of ADAM8 and suppress tumor cells proliferation, invasion and migration." (PMID 36506511, 2022). "The metalloprotease-disintegrin ADAM8 is critically involved in the progression of pancreatic cancer." (PMID 35216088, 2022). "For example, propofol was shown to prevent the progress of pancreatic cancer under hypoxic conditions via ADAM8 and affect the proliferation and apoptosis of cardia cancer cells via the MAPK/ERK signaling pathway." (PMID 35535311, 2022). "The metalloprotease-disintegrin ADAM8 is highly expressed in pancreatic cancer cells and is correlated with an unfavorable patient prognosis." (PMID 33578644, 2021). "For example, propofol restrains pancreatic cancer cells growth and metastases via elevating miR-328 and depressing ADAM Metallopeptidase Domain 8 (ADAM8)." (PMID 34775376, 2021). "Peptidomimetics were shown to be useful to inhibit ADAM8 multimerisation and hence autoactivation in pancreatic cancer." (PMID 32698506, 2020). "Several studies have shown that ADAM8 is highly expressed in a variety of malignant tumour tissues, such as colon cancer, glioma, lung cancer, liver cancer, pancreatic cancer and gastric cancer, and promotes tumour invasion and metastasis." (PMID 32954649, 2020). "The membrane localization of ADAM8 in pancreatic cancer cells suggested that ADAM8 was complexed with β1 integrin thereby enhancing cell migration and invasiveness." (PMID 32954649, 2020). "In contrast, a peptidomimetic inhibitor of ADAM8 reduced tumour growth of pancreatic tumour cells in a xenograft model but was also able to impair tumour growth in a KRAS-driven pancreas cancer model and significantly prolonged overall survival." (PMID 32698506, 2020). "Transfer experiments also showed a promigratory role of ADAM8 on leukocytes (unpublished data) and on breast and pancreatic cancer cells." (PMID 28260841, 2017). "Also the peptidomimetic ADAM8 inhibitor can improve survival in murine Kras‐driven pancreatic cancer model." (PMID 33314720, 2021). "ADAM8 levels were induced under hypoxia in pancreatic cancer cells." (PMID 24375628, 2014). "Hence, ADAM8 represents a novel target for the treatment of pancreatic cancer." (PMID 32698506, 2020).
pancreatic cancer (continued). "ADAM8 inhibition could also decrease metastasis of implanted pancreatic tumor cells." (PMID 28260841, 2017). "Furthermore, using a novel cyclic peptide inhibitor that binds to the ADAM8 disintegrin domain, they demonstrated a profound reduction in tumor burden and metastasis in orthotopic xenograft and KrasG12D transgenic mouse models of pancreatic cancer." (PMID 24375628, 2014). "The majority of pancreatic tumors strongly express A disintegrin and metalloproteinase (ADAM) 8 (ADAM8)." (PMID 39412616, 2025). "BK-1361 is a peptidomimetic ADAM8 inhibitor, affecting ADAM8 function, and leading to less ERK1/2 and MMP activation, with an anti-invasion effect in pancreatic cancer." (PMID 38755530, 2024). "ADAM8 regulates intracellular STAT3 levels via miR-181a-5p and NEAT1 in pancreatic cancer." (PMID 39412616, 2025). "Our present study revealed that the STAT3 signaling pathway is partially regulated by ADAM8 in pancreatic cancer, but only the STAT3 protein, not its mRNA, is dependent on ADAM8 expression." (PMID 39412616, 2025). "Hypoxia also occurs in pancreatic cancer, and some hypoxia-related molecules such as ADAM8, BX111, and CF129 have been identified to play crucial roles in the progression of pancreatic cancer, which might have potential as prognostic biomarkers and therapeutic targets for pancreatic cancer." (PMID 35789607, 2022).
asthma (19 papers, 2008 to 2024). "Investigations have revealed that ADAM8 is not only implicated in the pathogenesis of asthma but also closely associated with the severity of asthma and indices of pulmonary function." (PMID 39588470, 2024). "From this perspective, a disintegrin and metalloprotease 8 (ADAM8) is of particular interest since it has been identified as a signature gene associated with moderate to severe asthma." (PMID 27458083, 2016). "A disintegrin and metalloproteinase 8 (ADAM8) has been identified as a signature gene associated with moderate and severe asthma." (PMID 27458083, 2016). "A genomic study has recently reported a link between ADAM-8 single nucleotide polymorphisms and asthma in humans." (PMID 20034386, 2009). "ADAM-8 is another member of the ADAM family potentially associated to asthma." (PMID 20034386, 2009). "In individuals with asthma, ADAM8 is predominantly expressed within eosinophils in sputum samples, and its expression is significantly elevated compared to that of the control group." (PMID 39588470, 2024). "While the expression of Adam8 under normal circumstances is minimal, Adam8 can be upregulated in a variety of pathologic conditions, including asthma, liver injury, and, most notably, cancer." (PMID 37370863, 2023). "In our Nb infection model, lung cells and a fraction of proximal clustering MLN cells also express genes associated with asthma or involved in pathways targeted by drugs for asthma treatment like Cysltr1, Plac8, or Adam8." (PMID 35950748, 2022). "The promigratory function of ADAM8 in leukocytes has been previously reported in asthma and sterile lung inflammation." (PMID 35132956, 2022). "Apart from the liver, ADAM8 upregulation has been described for other chronic inflammatory diseases such as asthma, COPD, and atherosclerosis." (PMID 33814981, 2021). "By contrast, others have reported that ADAM8 knockout exacerbates asthma or COPD by enhancing apoptosis." (PMID 33814981, 2021). "A proinflammatory role of ADAM8 has been described in a few inflammatory disorders including acute lung inflammation and asthma." (PMID 33814981, 2021). "On the other hand, some reports showed that ADAM8 facilitates neutrophil migration to the airways in severe asthma and COPD." (PMID 33195308, 2020). "Nevertheless, there is a controversy about its function in asthma, ADAM8 can induce or inhibit the transmigration of leukocytes in airway inflammation of asthma." (PMID 33195308, 2020). "Taken together, pharmacological ADAM8 inhibition appears as promising novel therapeutic strategy for the treatment of asthma." (PMID 27458083, 2016). "In sputum and endobronchial biopsies obtained from moderate and severe asthmatic patients, and in lungs of experimental murine asthma model, ADAM8 is more abundant." (PMID 27458083, 2016). "Studies in mice have demonstrated that the severity of asthma can be reduced by either transgenic knock-out or by antibodies blocking ADAM8 function, highlighting ADAM8 as potential drug target for asthma therapy." (PMID 27458083, 2016). "Among these, five (LPA, ADAM8, DOCK1, GPR123 and PTPRE) presented modest associations with asthma, atopy or allergic asthma." (PMID 18682798, 2008). "In addition, increased expression of ADAM8 was observed in the sputum and endobronchial biopsies of patients with moderate and severe asthma." (PMID 35619695, 2022). "Different studies found that ADAM8 knockout or inhibition can attenuate asthma." (PMID 33814981, 2021). "ADAM8 plays a proinflammatory role in asthma airway inflammation, and ADAM8-deficient mice failed to develop an experimental model of asthma." (PMID 33195308, 2020). "Therefore, ADAM8 inhibition by BK-1361 provides a promising opportunity for the treatment of asthma." (PMID 27458083, 2016).
asthma (continued). "As membrane-bound CD23 is processed by ADAM-8 leading to ectodomain cleavage and resulting in the release of a soluble form of CD23 (sCD23), the low-affinity IgE receptor, ADAM-8 could take part to the cascade of events leading to asthma phenotype." (PMID 20034386, 2009). "The first report to suggest an ADAM-8 implication in asthma was published in 2004." (PMID 20034386, 2009). "Taken together, these data strongly suggest that ADAM-8 is a key mediator in asthma." (PMID 20034386, 2009). "ADAM-8 also cleaves important effectors in asthma pathology such as pro-TNF-α and L-selectin." (PMID 20034386, 2009). "In addition, polymorphisms in ADAM33 are associated with adult-onset asthma and disease severity, and this gene and ADAM8 may contribute to the remodelling process that occurs with asthma progression." (PMID 26986948, 2016). "In this study, we assessed the potential therapeutic effect of BK-1361, a specific peptide inhibitor of ADAM8, in treatment of the OVA-induced murine model of asthma." (PMID 27458083, 2016). "Here we show that in a pure TH2-skewed strain (Balb/c strain), ADAM8 facilitated the infiltration of eosinophils and TH2 cells and thus participated in the aggravation of asthma airway inflammation." (PMID 27458083, 2016). "Interestingly, studies in endobronchial biopsies derived from patients with asthma reveal an increase in the expression of certain genes involved in asthma progression such as disintegrin and metalloprotease (ADAM) 33, ADAM8, eotaxin, and CCL19 in ASM layer." (PMID 36012240, 2022). "Neither ADAM33 antibody cross-reacted with recombinant ADAM8 and ADAM12, which have been associated with asthma and show high homology with ADAM33." (PMID 27489884, 2016). "ADAM8−/− mice do not have an obvious pathologic phenotype however we recently showed that the lack of ADAM8 renders mice more resistant to induction of experimental asthma and that this phenotype was in part T cell dependent." (PMID 20856819, 2010). "Correlation analysis with pulmonary function tests has demonstrated a marked negative correlation between ADAM8 levels in sputum and the FEV1, an indicator of pulmonary function, suggesting a close relationship between ADAM8 levels in sputum and the severity of asthma." (PMID 39588470, 2024).